METTL22 (methyltransferase 22, Kin17 lysine)
Description:
Protein N-lysine methyltransferase. Trimethylates KIN at Lys-135 (in vitro).
Synonyms: C16orf68; FLJ12433; MGC2654
Tractability: PROTAC: ubiquitination databases record sites on it.
Gene: Protein-coding gene on chromosome 16 (8,621,682 to 8,649,654, forward strand). Ensembl gene ENSG00000067365.
Subcellular location: Nucleus
Subcellular location (Human Protein Atlas): Nucleoli rim; Nucleoplasm
Pathways (Reactome):
Metabolism of proteins: Protein methylation
Gene Ontology:
Molecular function: heat shock protein binding; protein binding; protein-lysine N-methyltransferase activity; protein methyltransferase activity
Biological process: DNA damage response
Cellular component: nucleolus; nucleoplasm; nucleus; protein-containing complex
Genetic constraint (gnomAD): Loss-of-function variants: 51 observed, 46.66 expected, observed/expected ratio (o/e) 1.09, 90% interval 0.87 to 1.38. The upper end of that interval is the gene's LOEUF score, 1.38, which puts it in group 5 of 6, group 1 being the genes least tolerant of losing a copy. Missense variants: 654 observed, 519.39 expected, observed/expected ratio (o/e) 1.26, 90% interval 1.18 to 1.34. Synonymous variants: 248 observed, 213.56 expected, observed/expected ratio (o/e) 1.16, 90% interval 1.05 to 1.29.
Homologues: Orthologues: chimpanzee METTL22 (99% identical), macaque METTL22 (95% identical), guinea pig METTL22 (79% identical), dog METTL22 (77% identical), rat Mettl22 (77% identical), mouse Mettl22 (77% identical), rabbit METTL22 (76% identical), pig METTL22 (75% identical), zebrafish mettl22 (49% identical), Drosophila melanogaster CG10584 (25% identical).
Diseases named in the same sentence as METTL22 in open-access papers:
METTL22 is named in the same sentence as 1 disease in open-access papers, as found by Europe PMC text mining. Sharing a sentence is not in itself a finding about the gene and the disease. The quoted sentences say what the papers report.
tumor (1 paper, 2024). "METTL21B and METTL22 displayed tumor suppressive functions without activating Src (as assessed by colony formation, migration, and invasion assays) when Flag-METTL21A and Myc-METTL22 were overexpressed." (PMID 39309445, 2024).